RPA4 (replication protein A4)
Description:
As part of the alternative replication protein A complex, aRPA, binds single-stranded DNA and probably plays a role in DNA repair. Compared to the RPA2-containing, canonical RPA complex, may not support chromosomal DNA replication and cell cycle progression through S-phase. The aRPA may not promote efficient priming by DNA polymerase alpha but could support DNA polymerase delta synthesis in the presence of PCNA and replication factor C (RFC), the dual incision/excision reaction of nucleotide excision repair and RAD51-dependent strand exchange.
Synonyms: HSU24186
Tractability: No criterion of Open Targets' tractability assessment is met for any kind of drug.
Gene: Protein-coding gene on chromosome X (96,883,908 to 96,885,467, forward strand). Ensembl gene ENSG00000204086.
Subcellular location: Nucleus
Subcellular location (Human Protein Atlas): Nucleoplasm
Pathways (Reactome):
DNA Replication: Activation of the pre-replicative complex
Gene Ontology:
Molecular function: protein binding; single-stranded DNA binding; telomeric DNA binding; DNA binding
Biological process: DNA damage checkpoint signaling; DNA repair; nuclear DNA replication; nucleotide-excision repair; DNA replication; DNA replication initiation; DNA recombination
Cellular component: DNA replication factor A complex; nucleoplasm; nucleus; chromosome, telomeric region; site of double-strand break
Homologues: Orthologues: Drosophila melanogaster RPA2 (23% identical), Caenorhabditis elegans rpa-2 (18% identical). Paralogues in human: RPA2 (44% identical), STN1 (15% identical).
Diseases named in the same sentence as RPA4 in open-access papers:
RPA4 is named in the same sentence as 3 diseases in open-access papers, as found by Europe PMC text mining. Sharing a sentence is not in itself a finding about the gene and the disease. The quoted sentences say what the papers report.
tumor (1 paper, 2016). "Interestingly, some of them function as tumor suppressors (e.g. BCL2L11, MXD1, WWOX, BNIP3L, and DMTF1) or are candidate tumor suppressors having anti-proliferative properties and DNA repair abilities (e.g. LRRC2, RPA4, PPP6R1, SPEN, RAP1GAP and CISH) (see discussion section)." (PMID 26918450, 2016).
RPA4 also shares sentences with these, for which no sentence is quoted: pancreatic cancer (1 paper); Rb (1).